INS (insulin)
Diseases named in the same sentence as INS in open-access papers (continued):
Sharing a sentence is not in itself a finding about the gene and the disease.
Obesity (continued). "As macrophage function is generally hampered by obesity and because insulin resistance promotes hyperglycemia, it is foreseeable that this condition provides the perfect storm for initial barrier breach followed by bacterial and/or bacterial product translocation." (PMID 35291443, 2022). "Thus, overall, FGF21 is an insulin-stimulated beneficial myokine that regulates energy metabolism and protects against chronic metabolic disorders such as T2D and obesity." (PMID 35563026, 2022). "Indeed, many metabolic phenotypes, including lipid metabolism, obesity, glucose response, and insulin sensitivity, can be transmitted to the host via fecal transplantation." (PMID 35889740, 2022). "In the present study, we showed that hTFAM overexpression in the BAT of mice exhibited marked resistance against age- and diet-induced obesity, produced higher energy expenditure, improved insulin secretory function and resistance, and increased mitochondrial function." (PMID 36046191, 2022). "Thus, here we will determine the impact of diet-induced-obesity (DIO) on brain insulin gene expression in brain areas well-established to have a role in energy balance regulation, the hypothalamus and the dorsal vagal complex (DVC)." (PMID 36244663, 2022). "In addition, the accumulated insulin can inhibit the decomposition of visceral fat, leading to the development of obesity." (PMID 35673358, 2022). "Additionally, the regulation of β cell mass is essential for the compensatory response of the endocrine pancreas to situations of increased insulin demand such as obesity." (PMID 35198097, 2022). "Therefore, it is difficult to evaluate if increased miR‐27a levels in OB groups reflect impaired insulin signalling or rather the grade of obesity." (PMID 34918493, 2022). "There are healthy obese individuals and those that become insulin resistant at a low BMI, suggesting that obesity itself is a correlate, not a cause, of pathophysiology." (PMID 35906462, 2022). "In addition to the effect of AT accumulation on glucose tolerance and insulin sensitivity, obesity amplifies a wide range of inflammatory diseases in multiple organs and attenuates wound repair 22-24,29,41-43." (PMID 35198063, 2022). "Understanding this pathway could aid in improving insulin BBB transport in CNS insulin dysregulated conditions such as obesity and Alzheimer’s disease." (PMID 37936681, 2022). "Moreover, sex-related differences in insulin signaling have been observed in obesity and metabolic syndrome animal models, which suggests that mechanisms of energetic homeostasis show sexual dimorphism in response to high fat- or high carbohydrates-diets." (PMID 36224569, 2022). "Authors also discuss obesity-induced inflammation in HS, which has an impact on insulin signaling." (PMID 36499573, 2022). "Moreover, obesity and inflammation are reported to decrease the transport of insulin to the brain through the BBB, and T2D patients show a decreased expression of IR in the brain." (PMID 35406040, 2022). "Additionally, as adiponectin promotes insulin sensitivity it supports a potential important player in the context of obesity." (PMID 35844529, 2022). "The alterations induced by arsenic on the macrophages that reside in the adipose tissue, which are essential in modulating insulin sensitivity and chronic inflammation during obesity are unknown." (PMID 35651975, 2022). "An eight-week randomised control trial in children and adolescents with obesity showed a change in microbiota (reduced number of Escherichia coli), weight and an improvement in insulin sensitivity and certain metabolic parameters after supplementation with Bifidobacterium breve BR03 and B632." (PMID 36013366, 2022). "In primary hepatocytes, we found that classical antidiabetic and insulin-sensitizer drugs, e.g., metformin and rosiglitazone, as well as micronutrients known to improve metabolism and obesity, e.g., the isoflavone genistein, specifically modulate the expression of these hepatokines." (PMID 35409319, 2022).
Obesity (continued). "Therefore, exercise along with thermogenic function in muscle prevents metabolic disorders such as obesity and insulin sensitivity." (PMID 36093083, 2022). "Other biomarkers that are altered in men with obesity include pro-inflammatory cytokines, insulin, and oxidative stress biomarkers, which have been hypothesised to increase prostate cancer risk." (PMID 35509091, 2022). "Indeed, the metabolically healthy obesity (MHO) phenotype has been defined as favorable lipid profile as well as normal or slight changes in insulin sensitivity, while in metabolically unhealthy obesity (MUHO), these criteria are affected abnormally." (PMID 35685490, 2022). "It had been found that the improvement of PCs on insulin sensitivity were not linked to inhibitory potential in obesity." (PMID 36145094, 2022). "Understanding the regulation of insulin removal from plasma and how it might be altered in people with obesity and T2D is therefore very important." (PMID 35054781, 2022). "This review will guide future research regarding the IFN family in obesity and insulin sensitivity." (PMID 36552805, 2022). "Taken together these results suggest that IN insulin may reduce food intake by influencing food reward processes and that women with obesity may be more sensitive to these effects than lean women." (PMID 35397638, 2022). "Studies in animals have demonstrated that butyrate increases insulin sensitivity while reducing inflammation and food intake; a decrease in butyrate concentration due to both pregnancy and obesity can further influence the maternal and thus the infant’s gut metabolism and immune system." (PMID 36619646, 2022). "Db/db and ob/ob mouse models of T2D and obesity treated with SGLT2i (luseogliflozin, ipragliflozin or dapagliflozin) demonstrate reduced blood glucose, augmented insulin and GLP-1 secretion, increased β-cell mass, β-cell replication and α- to β-cell conversion, and restored β-cell identity." (PMID 35180212, 2022). "We suggest that it may be related with the action of melanocortin 4 on the production of insulin by the β-cells of the pancreas, as in case of monogenic form of obesity." (PMID 35292917, 2022). "Although neither glucose nor insulin at age 4 differed between groups D+E (Q1-3→4), B (Q2-3→2-3) and F (Q1→2-3) in our study, their effect on later obesity and metabolic risk during childhood and adolescence needs to be evaluated." (PMID 35677718, 2022). "Indeed, deficiency or antagonism of the C3a receptor 1 protects mice against obesity, reduces AT inflammation and improves systemic insulin sensitivity." (PMID 35216336, 2022). "Notably, while ErbB4 deletion predisposes mice to metabolic alterations implicated in obesity, NRG1 administration is known to improve metabolic health in obese mice by lowering blood glucose, improving insulin sensitivity, and reducing caloric intake." (PMID 35220393, 2022). "In addition, succinic acid was involved in preventing obesity and improving glucose resistance and insulin sensitivity of wild-type mice in vivo experiments." (PMID 36140683, 2022). "Indeed, the deletion of miR-155 in mice prevented diet-induced obesity, improved insulin sensitivity, and abrogated adipocyte hypertrophy and adipose tissue inflammation." (PMID 36142173, 2022). "In another study of 30 NAFLD patients with elevated liver enzymes, obesity and type 2 DM, exenatide plus insulin was seen to improve steatosis from baseline in 28 (93.3%) patients, which was a significantly higher improvement rate than that observed with intensive insulin therapy." (PMID 34997159, 2022). "IL-1β and TNFα were identified as inducers of S100A9 in epidermis and dWAT while obesity-associated factors such as high glucose, insulin or SFA do not affect S100A9 expression." (PMID 35198063, 2022). "Furthermore, in women with normal weight and obesity central insulin led to an increase in FCR in the insula." (PMID 35715625, 2022).
Obesity (continued). "The increased fat oxidation promoted by PA might be the basis for the prevention and restoration of insulin sensitivity and reduction of metabolic syndrome in children with obesity." (PMID 35495947, 2022). "Then we sought to clarify the mechanism of action of SG on the reduction of LVM and, thus, we compared the effects of SG with those of a sham operation on BCAA, glucose and fatty acid metabolism as well as on insulin signalling in rats with diet-induced obesity." (PMID 35131692, 2022). "This could potentially exacerbate the metabolic effects of sarcopenic obesity given the decreased glucose uptake resulting from decreased muscle mass heightened by the inhibitory action of myostatin on insulin sensitivity." (PMID 35287731, 2022). "Furthermore, sleep disorders decrease carbohydrate tolerance, alter leptin and cortisol levels, thus modifying insulin sensitivity and favouring obesity and MS." (PMID 35896655, 2022). "In adults with obesity, detraining has been shown to partly or totally attenuate the metabolic benefits of exercise, with a significant increase in lipid accumulation, insulin resistance, and insulin levels." (PMID 35749411, 2022). "Interestingly, glutamine treatment can ameliorate obesity and related comorbidities in mice, consistent with previous observations that glutamine supplementation reduces obesity with an improvement in systemic insulin action 70,71." (PMID 35198059, 2022). "The study will direct the research towards other important roles that NTN-1 may play in obesity including the regulation of insulin sensitivity and oxidative stress." (PMID 36297056, 2022). "We hypothesized that DII and DIL could affect fat accumulation, fat distribution, inflammatory factors, and the metabolic phenotypes of obesity via different insulin responses." (PMID 36311488, 2022). "Through the comparison of various clinical indicators between T2DM macaques and T2DM patients, it is clearly found that all of them have experienced obesity, compensatory increase in fasting insulin, reduced postprandial glucose clearance, and decreased insulin secretion, significantly." (PMID 36140683, 2022). "However, when chronic energy surplus overcomes the buffering capacity of adipocytes, such as in obesity, this results in local insulin resistance as well as lipid dysregulation and local inflammation." (PMID 38938664, 2022). "Another hypothesis is that the low-grade inflammation that accompanies obesity leads to impaired peripheral tissue insulin sensitivity." (PMID 35885586, 2022). "Next, to further define the differential effect of obesity on the metabolic health of adult versus aged mice, we quantified plasma fasting insulin levels, as well as terminal epididymal adipocyte hypertrophy and hepatic pathology to assess the effect in multiple organs." (PMID 36550567, 2022). "FABP4 and fatty acids promote and regulate insulin secretion during obesity." (PMID 35647197, 2022). "Furthermore, B1R in adipose tissue controls the response to diet-induced obesity and its deletion protects from obesity and improves insulin sensitivity." (PMID 39086962, 2022). "Based on this, we suspect that inhibition of SPHK1 by CBD may be considered as a potential therapeutic approach to restoring normal insulin activity in obesity." (PMID 35628194, 2022). "Moreover, WBV affects the signaling pathways of obesity-related hormones, including insulin and leptin." (PMID 35456575, 2022). "Next, we wanted to investigate how the M1- and M2-like macrophage composition in the adipose tissue of individuals with obesity was related to systemic insulin resistance and other parameters relevant for metabolic function in the total patient cohort (Cohort 1 and 2, N=80)." (PMID 35480482, 2022). "Bariatric surgery improves insulin sensitivity and reduces glucocorticoid activation at the tissular level, under physiological and pathophysiological (obesity) conditions, irrespective of weight loss." (PMID 36246869, 2022).
Obesity (continued). "It is well known that hypothalamic inflammation reduces the responsiveness of POMC and NPY neurons in the ARC to the physiological actions of leptin and insulin and alters the normal activity of the orexigenic and anorexigenic peptides, thereby promoting energy imbalance and obesity." (PMID 35683029, 2022). "The adipokine network acts on a wide array of molecular targets and physiologic pathways, particularly insulin signaling, energy expenditure, food intake, and tissue inflammation to regulate systemic metabolic changes in response to obesity, OSA, and other factors." (PMID 35892989, 2022). "Moreover, butyrate has a good effect on preventing and suppressing obesity by improving the glucose homeostasis, insulin sensitivity, and function of the intestinal microbiota." (PMID 35293806, 2022). "Moreover, a combination therapy with insulin and metformin was more often observed in gestational diabetic mothers with obesity." (PMID 35663318, 2022). "Additionally, the activities of both IKKβ and JNK are elevated in obesity, and these kinases are essential for the production of inflammatory mediators and in the desensitization of insulin signaling." (PMID 36145191, 2022). "Without apparent toxicity, APC protects mice from high fat diet-induced obesity, decreases fasting glucose levels, enhances insulin sensitivity and reduces lipid levels in the serum and liver by suppressing CREB/CRTC2-mediated both gluconeogenic and SREBP transcriptions." (PMID 35017472, 2022). "Furthermore, our correlation analyses show that HFD-mediated gut microbiota abundance changes are significantly related to obesity phenotypes, e.g., body weight gain, fat mass, and insulin sensitivity." (PMID 35769373, 2022). "Multiple studies show that induced expansion of eVAT Tregs can alleviate obesity-induced inflammation and promote insulin sensitivity in mice fed a long-term high fat diet (HFD), indicating that disruption of eVAT Tregs is indeed a major driver for obesity-induced metabolic abnormalities." (PMID 36337732, 2022). "As per the carbohydrate-insulin model of obesity, carbohydrates elevate insulin secretion leading to fat storage in adipose tissue; therefore, we advise our patients to limit processed foods, carbonated beverages, fruit juices and added sugars to less than 10% of daily calorie intake." (PMID 36014956, 2022). "Especially unaltered 18F-FDG uptake may be unexpected given the general differences in insulin resistance between leanness and obesity." (PMID 35432192, 2022). "Furthermore, inflammation, renal hemodynamic changes, insulin resistance and lipid metabolism disorders are all involved in the development and progression of obesity-induced nephropathy." (PMID 35054932, 2022). "Interestingly, conditional knock-out of all miR-29 family members in aged female POMCCremiR-29CKO mice resulted in late onset obesity, fat pad enlargement and insulin resistance." (PMID 35490865, 2022). "It has been suggested that central inflammation, impaired insulin transport regulation in the blood-brain barrier and diminished neuronal responses to insulin might promote these changes in fully developed obesity." (PMID 34728775, 2022). "This is consistent with reports of IN insulin-induced mood improvement in men with obesity." (PMID 35397638, 2022). "Iron restriction improves insulin sensitivity in obesity, leading to improved glucose levels." (PMID 35453417, 2022). "In addition, physical activity also helps reduce proinflammatory conditions such as obesity and insulin disturbances." (PMID 35911542, 2022). "Later by either inactivating miRNA-155 expression in a murine model or by administering exosomes derived from the control group to the obesity group, authors showed that insulin sensitivity was reestablished using both methodological approaches, thus validating miRNA-155′s role in IR." (PMID 35681526, 2022).
Obesity (continued). "However, a study by MacKay and Callaway demonstrated that the use of “standard” insulin had little effect on eating behavior, but large increases in food intake, eventually leading to obesity." (PMID 35662925, 2022). "Circulating levels of insulin and leptin are high in obesity." (PMID 35406618, 2022). "Such 50–50 patterns are common and typically occur in outbred populations, amongst many examples: Wistar rats have “low” and “high” responders in the test of cephalic insulin response to oral glucose, and Sprague Dawley rats present a dual sensitivity to diet-induced obesity." (PMID 36232804, 2022). "Furthermore, deletion of ABCC10 ameliorates diet-induced obesity in mice and leads to a better response during insulin and glucose tolerance tests." (PMID 36430292, 2022). "Many systemic factors, dysregulated in obesity and T2D, may contribute to BC, including insulin, insulin-like growth factor 1 (IGF1), glucose, lipids, inflammatory cytokines, immune cells, steroids, the autonomic nervous system, adipokines and the microbiome." (PMID 36358839, 2022). "Depletion of Blautia wexlerae in the gut may develop in participants with obesity, contributing to metabolic inflammation and insulin resistance." (PMID 36676929, 2022). "It has also been shown that obesity not only affects the reduction in insulin sensitivity during puberty from early stages, but may also be associated with its persistence in the years following puberty." (PMID 34666809, 2021). "This review provides an overview of these novel functions of the NMU system, including homeostatic or hedonic feeding behavior, obesity-related complications, insulin secretion, and inflammation, and summarizes each function in terms of the molecular aspects and therapeutic possibilities." (PMID 33921859, 2021). "The use of low doses of STZ induces the death of pancreatic beta cells through thealkylation of DNA, leading to a slight impairment of insulin secretion withsubsequent hyperglycemia, whereas hyperlipidic diets lead to obesity, insulinresistance and mild hyperglycemia." (PMID 34431921, 2021). "Léger's and LM-LBM equations indicated a higher prevalence of central obesity, general overweight/obesity or obesity, elevated fasting insulin, and CRP levels and low HDL-C in females at the upper tails of eGFR distributions compared with those on the lower ones." (PMID 34778125, 2021). "Impaired DNMT1-dependend promoter methylation increases the expression of various developmental genes including insulin (INS), IGF-1 (IGF1) and fat mass- and obesity-associated gene (FTO), which all promote insulin/IGF-1-PI3K-AKT- and FTO/amino acid-mediated activation of mTORC1." (PMID 33803410, 2021). "Coming back to the endocrine system, both insulin resistance and leptin resistance illustrate best how obesity status reprograms hormonal functions during obesity via modifying the interaction quality of energy balance-control hormones with their target tissues." (PMID 33450943, 2021). "Early after the administration of a high-fat diet (HFD), the sustained increase of caloric intake induces hyperphagia and glucose intolerance, which are followed by a compensatory increase in leptin and insulin secretion prior to the onset of obesity and diabetes." (PMID 34015524, 2021). "Altogether, these data demonstrate that exercise-induced amelioration of insulin sensitivity in the obesity state could be explained by exercise-mediated suppression of PTP1B and PTEN, at least in part, coupled with increased RhoA expression." (PMID 34234788, 2021). "Adiponectin can prevent the impairment of insulin signaling; hence CXCL8 may play a crucial and causal role in obesity-linked IR and T2DM." (PMID 34054797, 2021). "Similarly, at comparable leptin levels (i.e., equivalent amounts of fat mass), children with PWS had a better response to exogenous insulin than those with common obesity." (PMID 34830599, 2021).